CTLA4 (cytotoxic T-lymphocyte associated protein 4)
Diseases named in the same sentence as CTLA4 in open-access papers (continued):
Sharing a sentence is not in itself a finding about the gene and the disease.
cancer (continued). "Another study showed that PP2A dephosphorylates and inactivates AKT by mediating inhibitory CTLA-4 (cluster of differentiation 152) signaling in activated T cells, acting as a potential target for cancer immunotherapy." (PMID 37234102, 2023). "Immunotherapy involves targeting immune checkpoints, such as PD-1/PD-L1 or CTLA-4, to restore the immune system’s ability to recognize and attack cancer cells." (PMID 37987366, 2023). "The CTLA-4 (cytotoxic T-lymphocyte-associated protein 4, CD152) pathway is another commonly targeted pathway in cancer immunotherapy." (PMID 37033265, 2023). "CTLA-4 inhibitors block the CTLA-4 protein found on T cells allowing them to become activated against cancer cells." (PMID 37425564, 2023). "The efficiency of contemporary immunotherapeutic strategies against cancer, such as CTLA-4/PD-1, is increased by downregulating this axis." (PMID 37892995, 2023). "Despite the great success of CTLA-4 blocking in cancer treatment, the use of anti-CTLA-4 monoclonal antibodies still faces many limitations." (PMID 37419930, 2023). "Several agents were developed to target the signaling axes of different immune-checkpoint proteins, including CTLA-4 and PD-1 in T lymphocytes and the PD-L1 ligand in cancer cells." (PMID 37111629, 2023). "PD-L1 and CTLA-4 belong to the immune checkpoint molecules that are crucial in the regulation of the immune response against cancer cells." (PMID 37408208, 2023). "Co-inhibition of A2AR and PD-1 or CTLA-4 has been investigated in several types of cancer and proven promising for the clinical application." (PMID 37753093, 2023). "At present, numerous clinical trials are underway to investigate the effectiveness of BsAbs targeting CTLA-4 in treating various types of cancer." (PMID 37441075, 2023). "Along those lines, checkpoint inhibitors play a pivotal role in the treatment of various advanced-stage cancers, as evidenced by improved immune responses with PD-1/PD-L1 and CTLA-4 therapies." (PMID 38147032, 2023). "According to Kaplan–Meier plotter website, PILRA expression was positively associated with prognosis of cancer patients receiving immunotherapy, including anti-PD1, anti-PD-L1 and anti-CTLA-4." (PMID 37652967, 2023). "As previously discussed, immune checkpoint blockade is one of the most effective methods of cancer immunotherapy that can enhance antitumor responses by inhibiting inhibitory molecules such as PD‐1, PD‐L1, and CTLA4." (PMID 36618103, 2023). "On the other hand, PD-1 and CTLA-4 down-regulate the effect of T-cell activity and enable cancer cells to escape for antitumor immunosurveillance." (PMID 37242756, 2023). "CTLA4 is an immune-related receptor capable of suppressing T cell function in various types of cancers." (PMID 36701414, 2023). "Immune checkpoint blockade therapies (including anti-PD-1, anti-PD-L1, and anti-CTLA4) have become hot topics in cancer immunotherapy in the near past, and their therapeutic value in cancer has been recognized, changing the landscape of cancer treatment." (PMID 38129565, 2023). "Additional studies are crucial to explore the role of CTLA-4 polymorphisms and their involvement in CTLA-4 expression for an improved utilization in immunotherapy against cancer." (PMID 37107632, 2023). "A pan‐cancer analysis indicated that CTLA4 has a high prognostic value as a biomarker in some cancer types, including ccRCC." (PMID 36397666, 2023). "Immune checkpoint inhibitors (ICIs), such as programmed death-1/ligand 1 (PD-1/L1) inhibitors and cytotoxic T-lymphocyte-associated protein-4 (CTLA-4) inhibitors, are promising drugs that can enhance the immune system for cancer treatment." (PMID 38090496, 2023). "Immunotherapy, especially anti-CTLA-4/PD-1/PD-L1 antibodies, has been applied in multiple types of cancers." (PMID 38020179, 2023). "The anti-CTLA-4 mAb, therefore, prevents inhibitory signaling on cytotoxic T-cells and enhances the immune response against cancer cells." (PMID 37239166, 2023).
cancer (continued). "In recent years, CPIs targeting PD-1, PD-L1, or CTLA-4 have shown long-lasting efficacy in cancer treatment." (PMID 38022587, 2023). "Blocking inhibitory receptors such as PD-1, CTLA-4 or Lag-3 have reversed this exhausted state in clinical trials of T cells in cancer." (PMID 36768336, 2023). "PD-1 and its ligand PD-L1 have proven to be attractive candidates for cancer immunotherapy, and their blockade has shown clinical efficacy in several cancer types with notable success when combined with anti-CTLA-4 therapy." (PMID 37001529, 2023). "Immune checkpoint therapies, such as inhibitors targeting the PD-1/PD-L1 and CTLA-4 pathways, have ushered in a new phase in cancer treatment." (PMID 37950153, 2023). "It targets immune checkpoint molecules, including CTLA-4, PD-1, and PD-L1, and thereby enhances the immune response to cancer." (PMID 36900399, 2023). "Nowadays, the blockade of CTLA-4 and PD-1 or PD-L1 is an approved treatment method in many cancers, including RCC." (PMID 36768365, 2023). "Increased expression of CTLA-4 (brown staining) was confirmed in cancer tissues compared to normal tissues." (PMID 37107632, 2023). "The results showed BTN2A2 was associated with the CTLA4, MHC, chemokine, JAK-STAT signaling pathways, antigen processing and presentation, PD1 blockade cancer immunotherapy, immune cells-microRNAs interactions in the TME, and apoptosis." (PMID 37851374, 2023). "Ipilimumab (Yervoy®), a CTLA-4 blocking antibody, emerged as a notable breakthrough in modern cancer treatment, showing upfront clinical benefits in multiple carcinomas." (PMID 37711295, 2023). "CTLA4 was found to be significantly downregulated in both the tbLN and spleen of tbLN treated mice suggestive of superior drug distribution at site critical to generating anti-cancer effect upon localized delivery of anti-CTLA4 mAb." (PMID 37259163, 2023). "Therapeutic blockade of inhibitory immune checkpoint pathways (e.g., PD-1/PD-L1 and CTLA-4) has transformed the care of patients across multiple cancer types, including many formerly intractable advanced cancers." (PMID 38213329, 2023). "A previous study illustrated that CTLA4 blocked with ipilimumab (a blocking antibody of CTLA4) induces cancer regression in some metastatic RCC patients." (PMID 38006403, 2023). "Cancer cells can evade the immune system by upregulating inhibitory receptors and ligands on their cell surface, such as CTLA-4, PD-1, PD-L1/2, Lag-3, and Tim-3." (PMID 38136253, 2023). "Blocking inhibitory immune checkpoint proteins like PD-1, PD-L1, and CTLA-4 with monoclonal antibodies has revolutionized cancer treatment by counteracting cancer cells’ evasion of immune responses and restoring T cell function." (PMID 37564659, 2023). "Tremelimumab is another drug in this category, which mainly targets the CTLA-4 as well to help the immune system fight against malignancies." (PMID 37445721, 2023). "Anti-programmed cell death protein 1 (PD-1), anti-programmed death-ligand 1 (PD-L1), and anti-cytotoxic T-lymphocyte antigen 4 (CTLA-4) immunotherapies are commonly used in the treatment of various cancers." (PMID 37963835, 2023). "In the last decade, monoclonal antibodies (mAbs) targeting CTLA-4, PD-1, or PD-L1 have been developed and immune checkpoint inhibitors (ICIs) have become the main approach in cancer immunotherapy." (PMID 38067379, 2023). "The cancer survival rate can be prolonged, and the progress and development of cancer in preclinical tumor models can be delayed by combining RT with anti‐CTLA‐4,15 anti‐PD‐1,16 or anti‐PD‐L1 therapy methods." (PMID 35771026, 2023). "Blocking T cell inhibitory pathways has become the new cancer treatment approach and immunological suppressive pathways involving CTLA-4 and PD-1 are actively studied." (PMID 36813833, 2023).
cancer (continued). "Directly targeting immune evasion by blockade of PD-1, PD-L1, and CTLA-4, has led to the development of various ICIs, which have proven to be successful immunotherapies for multiple cancers, including HCC." (PMID 36768686, 2023). "Immunotherapies for cancer, such as the blockade of CTLA-4 and PD-1, often result in severe autoimmunity as a side effect." (PMID 37441075, 2023). "For example, drugs that block immune checkpoint inhibitors, such as anti-CTLA-4 and anti-PD-1/PD-L1, have been approved for use in several types of cancer and have shown promising results in clinical trials." (PMID 37031434, 2023). "We obtained the clinical data of LUAD patients treated with CTLA-4 or/and PD-1 from The Cancer Immunome Atlas (TCIA) database." (PMID 36941988, 2023). "Antibodies (Abs) that specifically block ICs, also named immune checkpoint inhibitors (ICIs), including anti-CTLA-4, anti-PD-1, and anti-PD-L1, are transforming cancer therapies by enhancing anti-cancer immunity." (PMID 38130714, 2023). "Initially, two humanized anti-CTLA-4 antibodies (Ipilimumab and Tremelimumab) entered clinical trials in patients with advanced cancer in 2000." (PMID 36810034, 2023). "A number of inhibitory immunoreceptors have been identified and studied in cancer in past decades, including but not limited to PD-1, PD-L1, CTLA-4, LAG3, HAVCR2, TIGIT, CD69 and CD40." (PMID 37989761, 2023). "Monoclonal antibodies like anti‐PD‐1/PD‐L1 agents and anti‐CTLA‐4 antibodies, cancer vaccines, oncolytic viruses and adoptive T cell therapy have been discussed in brief." (PMID 36289059, 2023). "Antibodies against immune checkpoint receptors, such as anti-CTLA4 and anti-PD-1, has clearly proven the therapeutic potential of antigen presentation and T-cell response against cancer." (PMID 37491263, 2023). "We noted that the expression levels of PTGS2 and CTLA4 were highly heterogeneous across various cancer types." (PMID 38201508, 2023). "The identification of genetic modifiers of CTLA-4 holds promising clinical implications, particularly in guiding the selection of checkpoint inhibitor therapies for cancer patients and predicting the likelihood of severe adverse effects." (PMID 38055819, 2023). "Our analysis revealed a significant correlation (p < 0.05 between DNMT1 and ADORA2A, IL10RB, and CTLA-4 in certain cancers." (PMID 37628671, 2023). "This study also reports the role of immunotherapy in cancer treatments, contemplating the anti-CTLA4, anti-PD-L1 and anti PD-1 action in lymphocyte T cells." (PMID 36721805, 2023). "These two immune checkpoints are now emerging as promising targets in the post-PD-1/CTLA-4 era in cancer immunotherapy." (PMID 37332070, 2023). "Recently, immune checkpoint blockers, including anti-PD-1/PD-L1 antibodies and anti-CTLA-4 antibodies, have been applied clinically in the treatment of several cancer types." (PMID 36793737, 2023). "These drugs target and block interactions between immune checkpoint proteins such as PD‐1/PD‐L1 and CTLA‐4 to restore the ability of T cells to recognize and attack cancer cells." (PMID 38062888, 2023). "ICIs, including antibodies targeting programmed cell death protein 1 (PD-1), programmed death-ligand 1 (PD-L1), and cytotoxic T-lymphocyte-associated protein 4 (CTLA-4), unleash the immune system to recognize and attack cancer cells." (PMID 37626657, 2023). "In animal models and clinical trials, the combination of a CTLA-4 and PD-1/PD-L1 blockade demonstrated a synergistic effect in eliminating cancer cells, leading to improved survival outcomes for cancer patients." (PMID 37111629, 2023). "The discovery of immune checkpoints, including cytotoxic T lymphocyte protein 4 (CTLA4), PD-1, and PD-L1, was a breakthrough in cancer immunotherapy." (PMID 37662925, 2023). "Elucidating the significant parameters that determine anti-CTLA-4 BsAbs potency and persistence will be essential as the field progresses to evolving strategies to address obstacles specific to each type of cancer." (PMID 37441075, 2023).
cancer (continued). "Our findings indicate that patients with high CXCL scores had elevated levels of PD-L1/CTLA4, high IPS scores, and a high frequency of cancer gene mutations." (PMID 36969851, 2023). "The antibodies against immune checkpoint receptors have been exploited to conquer cancer by inducing T cell response, such as the antibodies against CTLA4, PD-1, PDL-1 and some alternative antibody formats (scFvs, Fabs, scAbs and VHHs)." (PMID 37491263, 2023). "Cancers with MMR and DSBR deficiencies show increased sensitivity to immune checkpoint inhibitors targeting the CTLA-4 and PD-L1/PD-1 pathways as a result of their increased immunogenicity." (PMID 37408208, 2023). "Our results collectively suggest that EC.SENESCENCE.SIG also serves as a reliable pan-cancer prediction model for anti-PD-L1/PD1 or anti-CTLA-4 immunotherapy response." (PMID 36978029, 2023). "Inhibitors of these checkpoints, such as anti-PD-1 and anti-CTLA-4 antibodies, have been approved to treat ccRCC and other cancers and have shown promise in improving patient outcomes." (PMID 37175653, 2023). "Curcumin, with a well-known modulatory effect on the expression of PD1 and CTLA-4, can act alongside immune checkpoint blockers to prevent cancer progression." (PMID 37765192, 2023). "Here we report that treatment of human lymphocytes with cfChPs isolated from sera of cancer patients led to marked activation of the immune checkpoints PD-1, CTLA-4, LAG-3, NKG2A, and TIM-3." (PMID 38274821, 2023). "Based on this concept, monoclonal antibodies (mAbs) targeting CTLA-4, PD-1, or PD-L1 have been developed and immune checkpoint inhibitors (ICIs) have become the main approach in cancer immunotherapy." (PMID 38067379, 2023). "MSI-H has recently been approved by the Food and Drug Administration as a genetic test to select patients for immunotherapy targeting PD-1 and/or CTLA-4 in many cancer types." (PMID 37062830, 2023). "These CTLA-4 inhibitors have already been used in clinical studies for treatment of several cancer types." (PMID 37492373, 2023). "Prolonged antigen exposure, which is common in cancer, can lead to tolerized T cells via CTLA-4 expression." (PMID 38406785, 2023). "Combination therapies manipulating the early regulator of T cell self‐reactivity (CTLA‐4) and a later regulator of T cell exhaustion (PD‐1) have produced outstanding results in cancer, albeit with autoimmune side effects." (PMID 36727298, 2023). "A retrospective analysis was performed on 210 patients treated with PD-1 or CTLA-4 inhibitors at Barretos Cancer Hospital, Brazil." (PMID 36980349, 2023). "Combining inhibitory receptor blockage, such as anti-PD1/PD-L1 and anti-CTLA4, has been shown to reverse LT depletion and improve immune responses in various types of cancer." (PMID 36763585, 2023). "Combining oncolytic viruses with anti‐checkpoint antibodies such as anti‐PD‐1, anti‐PDL‐1, and anti‐CTLA4 or CAR‐T cells can be effective in cancer therapy in a synergistic fashion." (PMID 36618103, 2023). "ICIs, mainly targeting CTLA4, PD-1, and PD-L1, has achieved remarkable success in the past decades, which has improved the outcomes of patients with advanced-stage cancer." (PMID 36960074, 2023). "Cancer immunotherapy including the PD-1/PD-L1 and CTLA-4 blockade regimens has achieved remarkable anticancer efficacy and long-term survival." (PMID 36859386, 2023). "The CD80 (B7-1) and CD86 (B7-2) checkpoint proteins expressed by immune and cancer cells bind to CTLA-4 on T-cells and repress TCR/HLA-class-I-mediated activation." (PMID 37232754, 2023). "After the success of the PD-1/PD-L1 blockade and the CTLA-4 blockade in animal models for cancer treatment, the immune checkpoint blockade (ICB) therapy for cancer has gained significant attention." (PMID 38095856, 2023). "Cancer immunotherapy in the form of checkpoint inhibitors targeting CTLA-4, PD-L1 and PD-1 has made significant impact in the treatment of solid tumors." (PMID 37346042, 2023).
cancer (continued). "Current research continues to advance PD-1 and CTLA-4 combinatorial immunotherapy in the treatment of other cancers." (PMID 37928556, 2023). "In fact, it has been reported that methylation regulates the expression of PD-1, PD-L1, and CTLA-4 in different cancers." (PMID 37509517, 2023). "Immune checkpoint inhibitors (ICI) such as anti-CTLA-4, anti-PD-1, and anti-PD-L1 monoclonal antibodies have been successfully introduced in the therapy of a variety of cancer types." (PMID 37048617, 2023). "CTLA-4 inhibitors, ipilimumab and tremelimumab, received approval for use in different cancers, including colorectal cancer (CRC), melanoma, mesothelioma, NSCLC and RCC." (PMID 37767098, 2023). "Taking advantage of CTLA-4 and PD-1 immunosuppressors to treat malignant tumors has also been successful in many tumors." (PMID 37342196, 2023). "Lots of studies have shown lncRNAs have a positive correlation with the immune checkpoint molecules such as CTLA-4, PD-1and PD-L1 in human cancers." (PMID 36810034, 2023). "With the unveiling of clinical studies of programmed death receptor 1 (PD-1) and cytotoxic T-lymphocyte-associated protein 4 (CTLA4) inhibitors, immune checkpoint inhibitor (ICI)-based immunotherapy has shown encouraging efficacy in multiple cancer types." (PMID 36814910, 2023). "ICB targeting the PD-1–PD-L1 and/or CTLA-4 axes provides durable clinical benefits to patients who have cancers with MMR-d and high microsatellite instability." (PMID 36631610, 2023). "Therapeutic anti-CTLA4 antibody, ipilimumab (Ipi), potentiates cancer immunity by blocking the B7-CTLA-4 negative regulation of T cell priming during antigen presentation." (PMID 37568717, 2023). "The discovery of immune checkpoints, such as CTLA-4 and PD-1, has unquestionably aided the advancement of cancer immunotherapy." (PMID 37504362, 2023). "So far, five PD-1 or PD-L1 inhibitors and one CTLA4 inhibitor have been approved to treat various cancers based on improvements in overall survival." (PMID 36949947, 2023). "Honjo and Allison were awarded the 2018 Nobel Prize for their discovery of programmed death-ligand-1 (PD-L1) and cytotoxic T lymphocyte antigen-4 (CTLA-4), co-stimulatory factors that regulate cancer and autoimmune diseases." (PMID 37153541, 2023). "Numerous studies have shown that immune checkpoint blockade of CTLA-4 can unleash T cell-mediated therapeutic responses against cancer." (PMID 37838657, 2023). "The first ICI to be tested and approved for the treatment of cancer patients was the anti-CTLA-4 blocking antibody—Ipilimumab." (PMID 36835456, 2023). "Among cancer patients who received immunotherapy, early change of circulating B cells of patients who received combination immunotherapy anti-CTLA-4/PD-1 correlated to irAE." (PMID 38127423, 2023). "Currently approved combination therapies for cancer treatment include alpha-PD-1/PD-L1 in combination with chemotherapy, angiogenesis inhibitors, and alpha-CTLA-4." (PMID 37305384, 2023). "Factors that decrease immune function (e.g., PD-L1, CTLA-4, and IL-10) are significantly increased in the immune and cancer cells in cancer tissues." (PMID 37153541, 2023). "Blocking immune checkpoint molecules, including the CTLA4, PD-1, and PD-L1 molecules, was proposed as a highly effective anti-tumor treatment for most types of cancer, with a 20%–50% success rate in different clinical trials." (PMID 37138873, 2023). "In one of the studies with an immune checkpoint blockade targeting CTLA-4 and PD-1 using a mouse model, they showed that the gut bacteria have influence in the response tp cancer immunotherapy." (PMID 36839825, 2023). "Our findings showed that MLKL was positively correlated with the expression of immune checkpoints such as PD1, PD-L1, PD-L2, and CTLA4 in most cancer types, except for ICOSLG, CD200, CEACAM1, HHLA2, and VTCN1 in BUC." (PMID 37000317, 2023).